PRR20E (proline rich 20E)
Tractability: No criterion of Open Targets' tractability assessment is met for any kind of drug.
Gene: Protein-coding gene on chromosome 13 (57,167,197 to 57,170,218, forward strand). Ensembl gene ENSG00000234278.
Gene Ontology:
Molecular function: protein binding
Homologues: Orthologues: dog PRR20G (38% identical). Paralogues in human: PRR20A (100% identical), PRR20B (100% identical), PRR20C (100% identical), PRR20D (100% identical), PRR20G (53% identical).